CC2D1A (coiled-coil and C2 domain containing 1A)
Description:
Transcription factor that binds specifically to the DRE (dual repressor element) and represses HTR1A gene transcription in neuronal cells. The combination of calcium and ATP specifically inactivates the binding with FRE. May play a role in the altered regulation of HTR1A associated with anxiety and major depression. Mediates HDAC-independent repression of HTR1A promoter in neuronal cell. Performs essential function in controlling functional maturation of synapses (By similarity). Plays distinct roles depending on its localization. When cytoplasmic, acts as a scaffold protein in the PI3K/PDK1/AKT pathway. Repressor of HTR1A when nuclear. In the centrosome, regulates spindle pole localization of the cohesin subunit SCC1/RAD21, thereby mediating centriole cohesion during mitosis.
Synonyms: Freud-1; LGD2; FLJ20241; MRT3; TAPE; Aki-1; Freud-1/Aki1
Tractability: Antibody: its Gene Ontology location is reachable by antibodies, with high confidence. PROTAC: ubiquitination databases record sites on it; its protein half-life has been measured.
Gene: Protein-coding gene on chromosome 19 (13,906,160 to 13,930,884, forward strand). Ensembl gene ENSG00000132024.
Subcellular location: Cytoplasm; Nucleus; Cytoplasm, cytoskeleton, microtubule organizing center, centrosome
Subcellular location (Human Protein Atlas): Cytosol; Basal body; Nucleoli fibrillar center; Plasma membrane
Gene Ontology:
Molecular function: cadherin binding; DNA-binding transcription repressor activity, RNA polymerase II-specific; protein binding; RNA polymerase II cis-regulatory region sequence-specific DNA binding; DNA-binding transcription factor activity, RNA polymerase II-specific
Biological process: negative regulation of snRNA transcription by RNA polymerase II; positive regulation of canonical NF-kappaB signal transduction; regulation of transcription by RNA polymerase II
Cellular component: cytoplasm; cytosol; extracellular exosome; membrane; nucleus; centrosome
Genetic constraint (gnomAD): Loss-of-function variants: 67 observed, 126.59 expected, observed/expected ratio (o/e) 0.53, 90% interval 0.43 to 0.65. The upper end of that interval is the gene's LOEUF score, 0.65, which puts it in group 2 of 6, group 1 being the genes least tolerant of losing a copy. Missense variants: 1,185 observed, 1,302.6 expected, observed/expected ratio (o/e) 0.91, 90% interval 0.87 to 0.95. Synonymous variants: 477 observed, 533.77 expected, observed/expected ratio (o/e) 0.89, 90% interval 0.83 to 0.96.
Gene-disease validity (ClinGen):
ClinGen rates the evidence that CC2D1A causes each of these diseases.
complex neurodevelopmental disorder (autosomal recessive): Definitive. A disorder that involves more than one phenotype associated with the central nervous system, including but not limited to intellectual disability, autism, and seizures (epilepsy).
Homologues: Orthologues: chimpanzee CC2D1A (99% identical), macaque CC2D1A (92% identical), dog CC2D1A (91% identical), pig CC2D1A (89% identical), guinea pig CC2D1A (84% identical), rat Cc2d1a (83% identical), mouse Cc2d1a (82% identical), tropical clawed frog cc2d1a (52% identical), zebrafish CC2D1A (50% identical), Drosophila melanogaster l(2)gd1 (30% identical), Caenorhabditis elegans ccct-1 (24% identical). Paralogues in human: CC2D1B (40% identical).
Diseases named in the same sentence as CC2D1A in open-access papers:
CC2D1A is named in the same sentence as 24 diseases in open-access papers, as found by Europe PMC text mining. Sharing a sentence is not in itself a finding about the gene and the disease. The quoted sentences say what the papers report.
Intellectual disability (8 papers, 2013 to 2025). "CC2D1A, another hub protein identified in a disease-associated module, functions as a transcriptional repressor in neuronal cells and has been linked to autism spectrum disorder, intellectual disability, and depression." (PMID 41357518, 2025). "In addition, to highlight the role of several PDEs in normal and pathological neurodevelopment, we focused here on the deregulation of cAMP and/or cGMP in Down Syndrome, Fragile X Syndrome, Rett Syndrome, and intellectual disability associated with the CC2D1A gene." (PMID 33414502, 2021). "Cc2d1a is highly expressed in neurons and has been implicated in intellectual disability and autism spectrum disorder, Cc2d1b is expressed in myelinating glial cells and peripheral nerves, which indicates that its role and function might not be fully redundant with Cc2d1a." (PMID 31379499, 2019). "The role of CC2D1A in ciliary biology and how that relates to intellectual disability remain to be determined." (PMID 39168639, 2024).
autism (3 papers, 2018 to 2024). Persistent deficits in social interaction and communication and interaction as well as a markedly restricted repertoire of activity and interest as well as repetitive patterns of behavior. "Here, acquired non-Mendelian hereditary character in a genetically defined mouse model of autism (Cc2d1a +/−) correlates with the transcriptional alteration of five miRNAs." (PMID 39334949, 2024). "Tissues-specific (hypothalamus) Cc2d1a in conditional knock-out mice exhibit learning, memory and social deficits, hyperactivity, repetitive behaviors and anxiety, all of which are key features of autism and ID." (PMID 39334949, 2024). "In Cc2d1a heterozygous mice, we track Mendelian and non-Mendelian inheritance of autism, both of which induce variations in miRNAs levels." (PMID 39334949, 2024).
Anxiety (2 papers, 2018 to 2021). Intense feelings of nervousness, tension, or panic often arise in response to interpersonal stresses. "We have previously found that loss of Cc2d1a leads to a constellation of behavioral deficits: cognitive and social impairment, anxiety, hyperactivity, and repetitive behaviors." (PMID 29552027, 2018). "In parallel, we recently reported that Cc2d1a-deficient mice present with cognitive and social deficits, hyperactivity and anxiety." (PMID 29552027, 2018). "Forebrain-specific Cc2d1a-deficient mice 1a-cKO display an array of cognitive and social deficits, in addition to anxiety and hyperactivity." (PMID 29552027, 2018). "Results from the 1a/1b-dHETs suggest that partial loss of Cc2d1a in combination with a half dosage of Cc2d1b is sufficient to generate hyperactivity and anxiety." (PMID 29552027, 2018). "We generated Cc2d1b knockout (KO), Cc2d1a/1b double heterozygous and double KO mice, then performed behavioral studies to analyze learning and memory, social interactions, anxiety, and hyperactivity." (PMID 29552027, 2018). "Cc2d1a conditional knockout (1a-cKO) mice show learning and memory deficits, social deficits, hyperactivity, anxiety, and repetitive behaviors." (PMID 29552027, 2018). "Each of the Cc2d1 genes contributes to aspects of learning and memory and sociability, but Cc2d1a appears to be more critical for hyperactivity and anxiety." (PMID 29552027, 2018). "While in Drosophila, the loss of the ortholog of CC2D1A, lgd, is embryonically lethal, Cc2d1a conditional KO mice display deficits in neuronal plasticity and in spatial learning and memory, which are accompanied by reduced sociability, hyperactivity, anxiety, and excessive grooming." (PMID 33414502, 2021). "Both CC2D1A and CC2D1B are involved in learning and memory, while CC2D1A alone appears to contribute to anxiety and hyperactivity." (PMID 29552027, 2018). "Cc2d1b also differs from Cc2d1a, as it appears to have no role in social behavior, hyperactivity, and anxiety." (PMID 29552027, 2018).
ciliopathies (2 papers, 2021 to 2023). "Further investigations should be performed to determine any involvement of the CC2D1A gene in ciliopathy phenotypes such as Joubert syndrome." (PMID 34205586, 2021).
autosomal recessive non-syndromic intellectual disability (1 paper, 2026). Autosomal recessive form of non-syndromic intellectual disability. "CC2D1A is a multidomain scaffold protein implicated in transcriptional regulation and autosomal recessive non-syndromic intellectual disability (NSID), yet its molecular mechanism is still poorly understood due to a lack of structural information." (PMID 42047282, 2026).
cognitive deficits (1 paper, 2024). "Although the conditional brain-specific knockout mouse models showed cognitive deficits and autistic-like phenotypes when CC2D1A was lost in glutamatergic neurons, similar to homozygous mice, they also died after birth, indicating potential additional roles of CC2D1A during embryonic development." (PMID 39168639, 2024).
cystic kidneys (1 paper, 2024). "In line with this expression pattern, loss of cc2d1a led to cardiac heterotaxy, cystic kidneys, and abnormal CSF circulation via defective ciliogenesis." (PMID 39168639, 2024). "Tadpoles developed abnormal left–right patterning and cystic kidneys when we depleted cc2d1a using the CRISPR/Cas9 system." (PMID 39168639, 2024).
cystic renal disease (1 paper, 2024). "In summary, our report expands on the role of CC2D1A in normal development and its associated disease, which includes intellectual and developmental disability, congenital heart disease, and cystic kidney disease, establishing its essential role in ciliogenesis." (PMID 39168639, 2024). "We broaden the clinical spectrum linked to the CC2D1A gene by presenting a new clinical presentation, cystic renal disease, and show that CC2D1A is essential for nephrogenesis." (PMID 39168639, 2024). "In summary, we have added evidence for CC2D1A as a cause of a multisystem ciliopathy syndrome, expanding the spectrum of CC2D1A-related disease from neurodevelopmental and cardiac involvement to the currently included cystic renal disease, LR patterning and CSF circulation." (PMID 39168639, 2024).
malignant mesothelioma (1 paper, 2024). A malignant neoplasm of the pleura or peritoneum, arising from mesothelial cells. "In Diffuse Malignant Mesothelioma, CC2D1A silencing resulted in tumor growth inhibition in mice models." (PMID 38915036, 2024).
memory impairment (1 paper, 2021). "Together these results explain our data on the Cc2d1a/Freud-1 knockdown-induced spatiotemporal learning and memory impairment." (PMID 34948116, 2021).
ovarian carcinoma (1 paper, 2019). A malignant neoplasm originating from the surface ovarian epithelium. "The objective of the present study is to investigate if CC2D1A, one of the constituents of the 14-gene panel predicting early recurrence in ovarian cancer, modulates chemotherapy resistance in ovarian cancer." (PMID 31632917, 2019). "To test the extent to which CC2D1A expression contributes to chemotherapy resistance in vitro, we knocked down CC2D1A expression in two different ovarian cancer cell lines, PE04 and SKOV3ip." (PMID 31632917, 2019). "Western blot analysis detected the presence of CC2D1A at 100 kDa in various ovarian cancer cell lines." (PMID 31632917, 2019). "To determine the clinical significance of CC2D1A expression in primary ovarian carcinomas, we analyzed CC2D1A expression in 146 carcinoma samples by immunohistochemistry." (PMID 31632917, 2019). "Here, we show that CC2D1A protein expression was higher in cisplatin-resistant ovarian cancer cell lines compared to cisplatin-sensitive cell lines." (PMID 31632917, 2019). "Results from ovarian cancer TCGA dataset were further corroborated by immunohistochemical analysis of CC2D1A protein expression in tumor TMAs, which showed significantly higher 5-year survival rate in patients with low CC2D1A expression than in patients with high CC2D1A expression in tumor samples." (PMID 31632917, 2019). "Subsequent to the discovery of the CC2D1A as one of the constituent members of the 14-gene panel predicting early recurrence in ovarian cancer, we hypothesized that CC2D1A has a role in modulating chemoresistance of ovarian cancer." (PMID 31632917, 2019).
ovarian tumors (1 paper, 2019). "We had previously reported that elevated CC2D1A mRNA was associated with early recurrence in ovarian tumors." (PMID 31632917, 2019).
serous ovarian cancer (1 paper, 2019). "The expression pattern of CC2D1A in serous ovarian cancer or papillary serous endometrial cancer is also markedly higher than in surrounding stromal tissue." (PMID 31632917, 2019).
synucleinopathies (1 paper, 2016). "Thus, we can speculate that, at least for CC2D1A and SYTL5, the effects observed are not due to cytotoxicity, as membrane integrity is preserved, and these hits can be further tested as candidate therapeutic modulators in synucleinopathies." (PMID 27123591, 2016).
cancer (2 papers, 2018 to 2019). A tumor composed of atypical neoplastic, often pleomorphic cells that invade other tissues. "Consistent with previously reported nuclear and cytoplasmic role of CC2D1A, we observed both nuclear and cytoplasmic localization for CC2D1A in cancer cells." (PMID 31632917, 2019). "Mutations in the gene encoding CC2D1A cause a rare form of ID and ASD in humans, and this protein is emerging as a critical regulator of intracellular signaling with roles in cognitive function, immunity and cancer." (PMID 29552027, 2018).
CC2D1A also shares sentences with these, for which no sentence is quoted: autism spectrum disorder (2 papers); tumor (2); depression (1); Down syndrome (1); fragile X syndrome (1); infection (1); Joubert syndrome (1); pancreatic cancer (1); Rett syndrome (1).